IRF3 (interferon regulatory factor 3)
Diseases named in the same sentence as IRF3 in open-access papers (continued):
Sharing a sentence is not in itself a finding about the gene and the disease.
Shock (2 papers, 2015 to 2019). The state in which profound and widespread reduction of effective tissue perfusion leads first to reversible, and then if prolonged, to irreversible cellular injury. "Infection of Recipient IRF3/7-/- mice become apparent at the indicated times (Column 3) by onset of clinical symptoms (hunching, ruffled fur, swollen feet) indicating onset of CHIKV-induced hemorrhagic shock." (PMID 26447467, 2015).
tuberculosis (2 papers, 2013 to 2024). A chronic, recurrent infection caused by the bacterium Mycobacterium tuberculosis. "However, the cytosolic sensing of Mtb and IRF3-dependent type I IFN signaling are likely to be associated with the pathogenesis of tuberculosis, because IRF deficiency leads to a more protective phenotype against long-term Mtb infection in mice." (PMID 23653625, 2013). "Note that IRF3−/− mice are protected from long-term Mtb infection, indicating that cytosolic sensing of Mtb-DNA and type I IFN signaling may contribute to the pathogenesis of tuberculosis." (PMID 23653625, 2013).
urinary tract infection (2 papers, 2010 to 2023). "It is supposed that genetic expression of IRF3 may influence susceptibility to urinary tract infections." (PMID 36983379, 2023). "IRF3 is an important mediator in the regulation of the antimicrobial response during urinary tract infections." (PMID 36983379, 2023).
ventricular dilatation (2 papers, 2018 to 2021). "Induction of MI in irf3−/− mice showed reduced ventricular dilatation together with a marked decrease in infiltrated pro-inflammatory monocytes in comparison to MI in wild-type (wt) mice." (PMID 30443679, 2018).
vitiligo (2 papers, 2024). Generalized well circumscribed patches of leukoderma that are generally distributed over symmetric body locations and is due to autoimmune destruction of melanocytes. "In our study, we made a notable discovery, revealing for the first time the potential involvement of IRF3 in the pathogenic mechanism of vitiligo." (PMID 38660673, 2024). "IRF3, supported by co-localization analysis, was associated with vitiligo and holds potential as a therapeutic target." (PMID 38660673, 2024). "Piceatannol, acting as an inhibitor of IRF3, may play a role in modulating the pathogenic mechanism of vitiligo." (PMID 38660673, 2024). "Interestingly, our findings suggest a protective role of both MDSCs and Bilirubin against vitiligo, while IRF3 and CXCL10 may potentially increase the risk of vitiligo occurrence." (PMID 38660673, 2024). "Although our molecular docking validation demonstrated the affinity between Piceatannol and IRF3, further in-depth research and validation are necessary to explore the therapeutic potential of Piceatannol in vitiligo." (PMID 38660673, 2024). "Further research is required to ascertain whether Piceatannol can effectively treat vitiligo by inhibiting IRF3." (PMID 38660673, 2024). "We hypothesize that in vitiligo, IRF3 might contribute to the development of the condition by promoting the release of CXCL10." (PMID 38660673, 2024). "Notably, we identified IRF3 as a potential novel therapeutic target for vitiligo." (PMID 38660673, 2024).
anaphylaxis (1 paper, 2023). An acute hypersensitivity reaction that occurs from exposure to an allergen. "We further investigated the effect of IRF3 deficiency in anaphylaxis models." (PMID 37296614, 2023). "The alteration of IRF3 affected the production of granule contents in the mast cells and the anaphylaxis responses, including PCA- and ovalbumin-induced active systemic anaphylaxis." (PMID 37296614, 2023).
ataxia telangiectasia (1 paper, 2022). Ataxia-telangiectasia is the association of severe combined immunodeficiency (affecting mainly the humoral immune response) with progressive cerebellar ataxia. "STING/TBK1/IRF3 axis is found to be activated in neurons, which induces inflammatory cytokine production and leads to neuronal death in a rat model of ataxia-telangiectasia." (PMID 35936778, 2022).
atrophic gastritis (1 paper, 2020). "miR-365 was poorly expressed in GC and atrophic gastritis tissues and GC cell lines, while TLR4, CDX2 and IRF3 were overexpressed." (PMID 33292210, 2020). "In addition, Western blot detected that the phosphorylation of IRF3 in gastric tissue of atrophic gastritis was elevated (p < 0.05), and the expression of IRF3 did not change significantly (p > 0.05)." (PMID 33292210, 2020).
biliary atresia (1 paper, 2023). A rare, biliary tract disease characterized by progressive obliterative cholangiopathy of the intra- and extrahepatic bile ducts, occurring in the embryonic/ perinatal period, leading to severe and persistent neonatal jaundice and acholic stool. "They observed that TLR3 signaling led to the expression of CCL5 via NF-κB and IRF3 in bile duct cells, and they suggested the involvement of this signaling pathway in biliary atresia pathogenesis." (PMID 37511764, 2023).
bladder cancer (1 paper, 2025). "In addition, we demonstrated that poly (I:C) intensely increased the expression of RIG-I and p-IRF3 protein, which could be reduced by asparagine in bladder cancer cells." (PMID 39964752, 2025).
bronchiectasis (1 paper, 2013). Segmental, irreversible dilation of the bronchial tree resulting in the accumulation of secretions which leads to obstruction. "Since silencing hnRNP A1/A2 or SF2/ASF in human NSCLC cells reduced expression levels of IRF-3 protein, we next examined the expression of hnRNP A1/A2, SF2/ASF, and IRF-3 in 63 NSCLC tumor tissues, 39 non-tumor control tissues, and 26 bronchiectasis tissues." (PMID 23658645, 2013).
Chlamydia infection (1 paper, 2015). "To further characterize the mechanisms of IFN-β synthesis during Chlamydia infection of OE cells in vitro, we utilized specific inhibitory drugs to clarify the roles of IRF3 and NF-κB on both early- and late-phase C. muridarum infections." (PMID 25798928, 2015). "Conversely, our data shows that IRF3 likely plays a larger role early during Chlamydia infection in OE cells." (PMID 25798928, 2015). "To confirm our hypothesis that IRF3 is involved in the early synthesis of IFN-β during Chlamydia infection of OE cells, we examined the impact of specific inhibitors of IRF3 and NF-κB on total IFN-β secretion." (PMID 25798928, 2015). "Our data proposes that the initial wave of IFN-β synthesized early during Chlamydia infection is TLR3-dependent and occurs through pathways involving IRF3; while late stage IFN-β synthesis is triggered by the type-1 IFN secreted into the supernatants, and signals through pathways that require IRF7." (PMID 25798928, 2015). "We have not examined the roles of IRF3 and NF-κB prior to the 4hr time point to ascertain whether NF-κB plays a more impactful role very early during Chlamydia infection of the OE cells." (PMID 25798928, 2015). "Interestingly, we did not observe any effect on overall IFN-β synthesis when BX-795 was added late during Chlamydia infection, which suggest that IRF3 was not involved in the late-infection synthesis of IFN-β." (PMID 25798928, 2015). "However, the early IFN-β response to Chlamydia infection in OE cells is largely TLR3-dependent, which differs from the findings in peritoneal macrophages and implicates divergent pathways to IFN-β synthesis that converge and activate IRF3 in these two cell-types." (PMID 25798928, 2015).
Chronic colitis (1 paper, 2025). A chronic inflammatory disease of the large intestine (colon, cecum and rectum). "protein-mtDNA complex―STING―IRF3/NF-κB―IL-12 (T helper cell)―chronic colitis." (PMID 41153813, 2025).
chronic hepatitis B (1 paper, 2025). "Previous work has shown that both INTS10 and IRF3 expression are reduced in patients with chronic hepatitis B compared to individuals who have achieved spontaneous viral resolution." (PMID 41383743, 2025). "Nevertheless, the relationships among INTS10 expression, IRF3, and HBV replication in patients with chronic hepatitis B (CHB) have not been comprehensively examined." (PMID 41383743, 2025).
chronic hepatitis C (1 paper, 2019). "Inhibition of MafB in CD14+ monocytes purified from chronic hepatitis C patients induced elevated IFN-α1 secretion, which was accompanied by IRF3 phosphorylation." (PMID 31447817, 2019). "Importantly, MafB inhibition directly promoted IFN-α1 production, but not IFN-β, by CD14+ monocytes from chronic hepatitis C patients, which was accompanied by IRF3 phosphorylation." (PMID 31447817, 2019).
Cirrhosis (1 paper, 2021). A chronic disorder of the liver in which liver tissue becomes scarred and is partially replaced by regenerative nodules and fibrotic tissue resulting in loss of liver function. "In parallel, genes activated by LPS including myeloid differentiation factor 88 (Myd88) and interferon regulatory factor 3 (Irf3) were upregulated in inflammation and cirrhosis compared to advanced cirrhosis and HCC (all P < 0.001)." (PMID 33858327, 2021).
colorectal adenocarcinoma (1 paper, 2022). The most common type of colorectal carcinoma. "Midostaurin inhibited colorectal adenocarcinoma cell growth associated with the formation of dsDNA and ssDNA; the up-regulation of mRNA expression of cGAS, STING, IRF3, and IFNAR1; the down-regulation of Trex-1, c-Kit, and Flt3 protein expression." (PMID 36230769, 2022). "Midostaurin increased mRNA expressions of cGAS, IRF3, and IFNAR1 in colorectal adenocarcinoma cells and mouse spleen macrophages." (PMID 36230769, 2022).
contact dermatitis (1 paper, 2023). An inflammatory skin condition caused by direct contact between the skin and either an irritating substance or an allergen. "First, spinal expression of STING and spinal phosphorylation of TBK1 and IRF3 are decreased in mice with morphine injection, dry skin and contact dermatitis." (PMID 37122031, 2023). "Furthermore, DMXAA drastically increases spinal phosphorylation of TBK1 and IRF3 following morphine exposure, dry skin and contact dermatitis." (PMID 37122031, 2023). "Our current findings imply that intrathecal morphine injection, dry skin and contact dermatitis might inhibit spinal STING expression to reduce the phosphorylation of TBK1 and IRF3, causing acute and chronic itch." (PMID 37122031, 2023).
corneal infection (1 paper, 2019). A viral or bacterial infectious process affecting the cornea. "Importantly, mice that lack both IRF3 and IRF7 (IRF3/7 double knockout mice) have been described to suffer increased HSV-1 replication and display enhanced dissemination of this virus to several organs after corneal infection." (PMID 31114761, 2019).
Dengue virus infection (1 paper, 2016). "Dengue virus infection, in monocyte-derived dendritic cells, activates the IRF3/7/STAT1 and NF-κB anti-viral and inflammatory pathways, as well as Nrf2-dependent antioxidant genes." (PMID 27093399, 2016).
diabetic retinopathy (1 paper, 2026). "Phosphorylated IRF3 initiates signal transducer and activator of transcription 6 (STAT6) activation, amplifying IFN-β1 production, a process also observed in Toll-like receptor 4 (TLR4)-mediated blood–retinal barrier breakdown during diabetic retinopathy." (PMID 41487469, 2026).
Diamond-Blackfan anemia (1 paper, 2019). A congenital aregenerative and often macrocytic anemia with erythroblastopenia. "Formation of a multipartite complex including STING and S6K is needed to activate IRF3 in response to DNA sensing A ribosomal protein deficiency resulting in Diamond-Blackfan Anemia (DBA) impairs rRNA processing and ribosome biogenesis, resulting in activation of innate immune signaling." (PMID 31841110, 2019).
dilated cardiomyopathy (1 paper, 2025). Cardiomyopathy which is characterized by dilation and contractile dysfunction of the left and right ventricles. "M1, associated with dilated cardiomyopathy and cardiac muscle contraction, contained enhanced proteins like Myl4, Trpm4, Irf3 in LV." (PMID 39921206, 2025).
Erythema (1 paper, 2016). Redness of the skin, caused by hyperemia of the capillaries in the lower layers of the skin. "Similarly, mosquito transmission of DENV or needle-inoculation with concurrent feeding of uninfected mosquitoes prolonged viremia and increased erythema (redness of the skin) in “humanized” mice and increased DENV titers around peak viremia in mice lacking IRF3/7." (PMID 27310141, 2016).
Ewing sarcoma (1 paper, 2025). A small round cell tumor that lacks morphologic, immunohistochemical, and electron microscopic evidence of neuroectodermal differentiation. "Both IFNγ and IRF3 were predicted to be upstream regulators of the overlapping gene signatures induced by radiotherapy in Ewing sarcoma." (PMID 40858520, 2025).
foot and mouth disease (1 paper, 2017). A viral infectious disease that results in infection in cattle and swine, has material basis in foot-and-mouth disease virus, which is transmitted by contaminated fomites, or transmitted by ingestion of food contaminated with infected meat or animal products. "Recently, Ramírez-Carvajal has demonstrated that a constitutively active fusion protein of porcine IRF3 and IRF7 completely protects swine against foot and mouth disease by inducing a strong type I IFN response." (PMID 28977918, 2017).
fungal infection (1 paper, 2018). "The formation of the InsP3R-SEC5 complex not only promoted InsP3R-mediated [Ca2+]c elevation, which is necessary for macrophage phagocytosis, but also enhanced TBK1 activity to activate the IRF-3-dependent type I interferon innate immune response against fungal infection." (PMID 29703257, 2018). "To determine if the SEC5-TBK1-IRF-3 signaling cascade is involved in C. albicans infection, we analyzed the phosphorylation of TBK1 (p-TBK1) and IRF-3 nuclear translocation during fungal infection, the results of which showed that C. albicans stimulation increased p-TBK1 levels in RAW264.7 cells." (PMID 29703257, 2018).
gastric ulcer (1 paper, 2017). An ulcerated lesion in the mucosal surface of the stomach. "It has been reported that rebamipide, used in Japan for the treatment of gastric ulcers and other gastrointestinal disorders, inhibited the DSS-induced IRF3 upregulation." (PMID 28848431, 2017).
gingivitis (1 paper, 2019). A disorder involving inflammation of the gums; may affect surrounding and supporting structures of the teeth. "In comparison, gingivitis biofilm activated fewer genes (e.g., TLR4) and cariogenic biofilm suppressed CD14, IRAK4, and IRF3 transcription." (PMID 31448244, 2019). "Besides the upregulation induced by the commensal biofilm, we also found that gingivitis biofilm significantly up-regulated CD14; gingivitis and cariogenic biofilms both up-regulated IRAK2 transcription; while the cariogenic biofilm slightly suppressed CD14, IRAK4, and IRF3 transcription." (PMID 31448244, 2019).
gram-negative bacterial infections (1 paper, 2020). Infections caused by bacteria that show up as pink (negative) when treated by the gram-staining method. "A recent report documented that TLR4-TRIF signaling and the IRF-3-mediated type I IFN response play important roles for in vivo IL-1β processing and production in response to Gram-negative bacterial infection." (PMID 32373120, 2020).
hantavirus infection (1 paper, 2023). "Downstream within the TLR-signaling pathways are the IRF proteins, and of these proteins, specifically IRF3 is shown to be of great importance during hantavirus infection." (PMID 37766212, 2023).
hemorrhage (1 paper, 2015). Loss of blood from the vascular compartment to the exterior or into nonvascular body space as a result of rupture or severance of the blood vessels. "Urine from IRF3/7-/- mice was negative in all samples tested; however, hemorrhage-induced oliguria meant urine samples were difficult to obtain during the peak of hemorrhagic disease." (PMID 26447467, 2015).
Hypercholesterolemia (1 paper, 2022). An increased concentration of cholesterol in the blood. "Furthermore, the regulatory network of PMs derived from hypercholesterolemia mice enclosed IRFs, including IRF3 and IRF7, that were highly connected to IFN-β and the affected biological processes." (PMID 35224060, 2022).
injury (1 paper, 2024). Damage inflicted on the body as the direct or indirect result of an external force, with or without disruption of structural continuity. "In addition, type-I IFN produced from liver parenchymal cells in an IRF3-dependent manner was protective in alcoholic-induced liver injury by increasing IL-10 production and decreasing TNF-α production in NPCs." (PMID 38539789, 2024).
interstitial lung disease (1 paper, 2025). A diverse group of lung diseases that affect the lung parenchyma. "We previously demonstrated that interstitial lung disease developed largely independent of the IFN I signaling, and occurs in the absence of cGAS, IRF3, IRF7, and of IFNAR1." (PMID 40111902, 2025).
intestinal cancer (1 paper, 2020). "We then applied a cocktail of antibiotics (Abx) in this spontaneous intestinal cancer model, which revealed that 4 months treatment of Abx decreased tumorigenesis in both Apcmin/+ mice and Apcmin/+IRF3−/− mice." (PMID 33188184, 2020).
intestinal tumor (1 paper, 2020). "Here, we unexpectedly found that the IRF3 deficient mice are hyper-susceptible to the development of intestinal tumor in AOM/DSS and Apcmin/+ models." (PMID 33188184, 2020).
intrauterine growth restriction (1 paper, 2019). "Furthermore, vaginal inoculation of ZIKV early during pregnancy (at embryonic day 4.5) was associated with intrauterine growth restriction and fetal resorptions in WT females crossed with WT males, Ifnar1−/- females crossed with WT males, and IRF3−/-IRF7−/- females crossed with IRF3−/-IRF7−/- males." (PMID 31451049, 2019).
ischemic cardiomyopathy (1 paper, 2026). Ischemic cardiomyopathy is a cardiomyopathy in which a weakness in the muscle of the heart due to inadequate oxygen delivery to the myocardium with coronary artery disease being the most common cause. "Here we identify elevated Ser396/Ser398 phosphorylation of the type I interferon (IFN) response regulating transcription factor IRF3 in the myocardium of patients and male mice with ischemic cardiomyopathy." (PMID 41760613, 2026).
itch (1 paper, 2023). "Spinal down-regulations of TBK1 and IRF3 phosphorylation in these two chronic itch models are elevated by STING activation." (PMID 37122031, 2023).
lipidosis (1 paper, 2015). "The results of the present study showed that TLR4 signalling activated the MyD88/NF-κB and the TRIF/IRF3 pathway to elicit lung inflammation and lipidosis in the ApoE−/− WD mice." (PMID 25975841, 2015).
lupus nephritis (1 paper, 2025). Glomerulonephritis in the context of systemic lupus erythematosus. "These pathways are activated by key regulators such as IRF3, IRF7, and STAT1, which promote immune cell infiltration and contribute to organ damage, as seen in lupus nephritis inflammation." (PMID 39844998, 2025).